SALL4 (spalt like transcription factor 4)
Diseases named in the same sentence as SALL4 in open-access papers (continued):
Sharing a sentence is not in itself a finding about the gene and the disease.
tumor (continued). "In contrast, mice lacking Sall4 in the AY-CCA exhibited a robust reduction in gross tumor burden, evidenced by a significantly lower LW/BW ratio and diminished macroscopic tumor growth compared with Sall4 WTGFP." (PMID 40932240, 2025). "PAX5 transcripts are present at very low levels in normal tissue and are further reduced in tumours, whereas SALL4, ZNF770 and ZNF121 transcripts are upregulated in primary and metastatic tumours compared to normal colon." (PMID 40241172, 2025). "Compared to the SALL4 + IR group, tumor volume and weight were drastically lower in the vector + IR group." (PMID 38355684, 2024). "Consistently, tumor masses from the SALL4-silenced group show a reduced cellularity, a significant decrease in GLI1 and the proliferation marker Ki67 expression as well as increased apoptosis as indicated by increased expression of cleaved Caspase-3 (Cl." (PMID 38062245, 2024). "After the tumor reached a volume of 100 mm3, the mice (Vector and SALL4 groups) were randomized into two groups: those who received 10 Gy of radiation (in two doses, 5 Gy/fraction) and those that did not." (PMID 38355684, 2024). "It has also been shown that the SALL4 protein regulates gene expression and tumor progression through epigenetic modifications." (PMID 38355684, 2024). "Lentiviral-induced genetic depletion of SALL4 significantly suppresses tumor cell proliferation and correlates with the impairment of SHH signaling activity." (PMID 38062245, 2024). "The relationship between SALL4 and HDACs in the regulation of gene expression represents a nodal point in tumor biology as well as an opportunity for cancer treatments." (PMID 38062245, 2024). "As a tumor suppressor, miR-16 is expressed at low levels in GC tissues and specifically targets SALL4 at both the RNA and protein levels in GC cells." (PMID 38584262, 2024). "These in vivo data confirm the tumorigenic role of SALL4 in the regulation of SHH-dependent tumor growth." (PMID 38062245, 2024). "Grafts from control group develop progressively enlarging tumors, whereas SALL4-depleted tumor masses grow at a significantly slower rate." (PMID 38062245, 2024). "Significantly upregulated mRNA and protein expression of SALL4, Wnt3a and β-catenin in HCC tissues is associated with tumor differentiation, the TNM stage, tumor size, vascular invasion and liver cirrhosis in HCC patients." (PMID 38584262, 2024). "The tumor cells had clear cytoplasm and were diffusely spalt-like transcription factor 4 (SALL4)-positive." (PMID 38744791, 2024). "The rest of the cells at the primary tumor site acquired several unique mutations (in genes SRC, SALL4, BAX, SMAD3), but with a slower mutation rate (PT2 PT3, PT5)." (PMID 38685065, 2024). "The distribution of SALL4 expression was then assessed at the single cell level by analyzing tumor and stromal cells from patients with PDAC using in situ hybridization (RNAscope)." (PMID 36587397, 2023). "Although SALL4 expression was mostly evaluated in tumor cells, our findings identify this embryonic transcription factor as a new biomarker in PDAC‐derived stroma." (PMID 36587397, 2023). "Using univariate Cox analyses in the ICGC cohort, five parameters were identified as prognostic factors for OS, including the molecular classification of Moffitt (tumor subtypes), primary tumor site, tumor grade, and SALL4 expression." (PMID 36587397, 2023). "Consistent with results observed in other tumor types, our study pointed out a prognostic value of SALL4 expression in PDAC." (PMID 36587397, 2023). "SALL4 is expressed in germ cells and is an excellent marker for malignant GCTs, because most of the tumor cells stain strongly and uniformly positive." (PMID 37138865, 2023). "Only two independent risk factors for OS were determined in multivariable Cox analysis: tumor grade (P = 0.01) and SALL4 gene expression (P = 0.02)." (PMID 36587397, 2023).
tumor (continued). "For SALL4, intense staining was observed in the tumour parenchyma in both the nucleus and cytoplasm of the cells, in the high columnar cells of the periphery, and in the central cells of the tumour island." (PMID 37559082, 2023). "SMMC 7721 cells transfected with SALL4 mimic or inhibitor were injected into nude mice and we found SALL4 over expression significantly increased both the weight and volume of tumor and SALL4 inhibition suppressed the cancer growth in vivo experiments." (PMID 36575044, 2022). "Lysine Demethylase 3A (KDM3A), Forkhead-Box (FOX), B-cell lymphoma (BCL), and Krüppel-like factor (KLF) are the other genes that are repressed by SALL4 leading to promotion of tumor progression in cancer cells." (PMID 36010677, 2022). "Immunohistochemically, the tumor cells showed expression of SALL4 (sal-like protein 4), HNF1B (hepatocyte nuclear factor 1-beta), PAX8 (paired box gene 8), and α-FP (alpha fetoprotein)." (PMID 35204394, 2022). "In HCC, MSCs-derived exosomes transferred miR-15a to target cells and then suppressed proliferation, migration, and invasion of tumor cells via inhibiting the expression of spalt like transcription factor 4 (SALL4)." (PMID 35592419, 2022). "It is well known that SALL4 is a regulator of cell stemness in biological development and tumor growth." (PMID 36362083, 2022). "HOXA11-AS silencing inhibited tumor growth via upregulation of miR-3619-5p and downregulation of SALL4." (PMID 35216168, 2022). "We found that SALL4 expression was significantly lower in healthy tissues compared to tumor samples (p-value = 7.3 × 10−114)." (PMID 36362083, 2022). "A deregulated SALL4–RBBp4/NuRD pathway results in tumor suppressors’ gene silencing, such as PTEN in HCC cells, leading to PI3K/AKT pathway activation." (PMID 36362083, 2022). "In summary, cell scratch experiments were used to determine the migrated ability of tumor cells, our results about the cell scratch, migration, and invasion experiments identified that, SALL4 accelerated the tumor metastatic capacity." (PMID 36575044, 2022). "Other studies in different tumor types have also provided insightful evidence regarding SALL4 involvement in drug resistance." (PMID 36362083, 2022). "For another, SALL4 can also inhibit apoptotic proteins, miRNAs, or pathways to promote tumor development, such as miRNAs, PTEN, Bax, caspase-related pathway, and so on." (PMID 35216168, 2022). "Overall, as an oncogene, SALL4 plays a pivotal role in carcinogenesis in different types of normal and tumor tissues." (PMID 35216168, 2022). "Researchers have observed that 86.1% of BC cases have shown high SALL4 expression, and it is regulating different tumor suppressor genes, including E-cadherin (CDH1) and PTEN." (PMID 36362083, 2022). "The mining of the GEPIA database also demonstrated that SALL4 exhibited significant differences in the expression between tumor and normal tissues in COAD." (PMID 35692499, 2022). "Other significantly upregulated genes such as SALL4, FOXM1, MYCN, MEP1A and MYBL2 have also been reported to be significantly elevated in HCC and associated with tumor progression." (PMID 36212481, 2022). "Due to its roles in various carcinogenic processes, SALL4 becomes a new biomarker for tumor diagnosis and treatment." (PMID 35692499, 2022). "LCSL cells express liver stem cell markers, including epithelial cell adhesion molecule (EpCAM), cytokeratin 19 (CK19), OV6 and Sal-like protein 4 (SALL4), and account for approximately 10% of the overall tumor tissues." (PMID 35223840, 2022). "In other studies, real-time polymerase chain reaction (PCR) was used to determine the expression of SALL4 in fresh and distant tumor tissues of colorectal specimens and the level of serum peripheral blood mononuclear cells, and similar results were obtained." (PMID 35692499, 2022).
tumor (continued). "Multiple miRNAs, including the Let-7 member miR-98, have been reported to target SALL4 and regulate tumor cell growth, apoptosis, and metastasis in various tumor types." (PMID 34573282, 2021). "First, SALL4 is highly expressed and positively associated with BOLA3-AS1 in COAD tumor tissues, suggesting a positive regulation between them." (PMID 34746134, 2021). "The association between tumour stage and the breadth of CTA- and the SALL4-specific T cell response was analyzed, and more CTA- and SALL4-specific T cells were detectable in patients with early-stage HCC than in those with advanced-stage HCC (P = 0.0104)." (PMID 34496797, 2021). "Second, this work provides a novel viewpoint on how SALL4 interacts with cancer cell stemness, thereby participating in tumor metastasis and progression." (PMID 34746134, 2021). "Several lines of evidence suggest that overexpression of SALL4 in human cancers affects multiple cellular processes involved in tumorigenesis, tumor growth, and tumor progression." (PMID 33644042, 2021). "High expression of SALL4 is correlated with the early steps of tumor development, metastasis to lymph nodes, poor prognosis, and invasion in various malignancies." (PMID 33745265, 2021). "Consistently with our in vitro results, SALL4 overexpression and miR-497-5p silencing promoted tumor xenograft’s growth." (PMID 34732693, 2021). "After being stratified by tumor stage, SALL4 overexpression predicted poor prognosis in stage III GC patients (P = 0.05), but not in patients with other stages of GC." (PMID 33644042, 2021). "To explore how SALL4 affects tumor behavior, especially the molecular mechanisms relevant to SALL4 in GC, we identified the relevant pathways of SALL4 and its co-expressed genes by pathway enrichment analysis and WGCNA." (PMID 33644042, 2021). "SALL4 is upregulated, and its expression positively correlates with tumor stage, metastasis to lymph nodes, and poor differentiation in CRC samples." (PMID 34944911, 2021). "Our findings revealed that the co-expression of LINC-ROR and SALL4 was significantly correlated with each other in the early steps of tumor development in patients." (PMID 33745265, 2021). "We also plotted the area under the ROC curves (AUCs), which illustrated strong separation between the tumor and normal tissues, with an AUC of 0.954 for SALL4." (PMID 33644042, 2021). "In contrast, the AFP-specific T cell response showed correlations with different tumour characteristics opposite to those of the CTA/SALL4-specific T cell response." (PMID 34496797, 2021). "After 3 weeks, SALL4 cell- and anti-miR-497-5p cell-injected mice showed a significantly higher tumor volume and weight than control groups." (PMID 34732693, 2021). "Due to its oncogenic role, SALL4 has emerged as a tumor marker in many tumors, especially germ cell tumors." (PMID 34732693, 2021). "Previous studies demonstrated that serum SALL4 mRNA levels in CRC patients correlated significantly with the degree of tumor invasion and differentiation with high sensitivity and specificity (96% and 95%, respectively), according to ROC analysis." (PMID 34067294, 2021). "There was an association between the underexpression of LINC-ROR and sex, stage of tumor progression, tumor type, and location of tumor (p < 0.05), and H.pylori infection with SALL4 expression (p = 0.036)." (PMID 33745265, 2021). "The up-regulated group plays an important role in tumor stemness, drug resistance, apoptosis, cell proliferation, and invasion, highlighting the need to further the current understanding of SALL4 regulation in GC." (PMID 33644042, 2021). "When HCC progresses to a certain extent, tumour cells expressing SALL4 escape recognition and killing by T cells, and the T cell repertoire changes dramatically at different stages of HCC." (PMID 34496797, 2021).
tumor (continued). "Next, to investigate the oncogenic activity of SALL4 in ccRCC tumorigenesis in vivo, tumor formation was evaluated by subcutaneous inoculation of 786-O sublines in nude mice." (PMID 32513235, 2020). "By analyzing the correlation between SALL4 methylation status and its mRNA expression, we found that six methylation regions of SALL4 were markedly hypomethylated in ccRCC tumor samples in comparison with paired normal kidney samples." (PMID 32513235, 2020). "Tumor tissues from control and SALL4 knockdown groups were collected for the detection of gene and protein expression." (PMID 32489324, 2020). "Transplantation of SALL4-expressing cells into immunodeficient mice gives rise to subcutaneous tumor growth and tumefaction of many organs." (PMID 32098783, 2020). "we found that downregulation of SALL4 in ccRCC cells resulted in a dramatic decrease in tumorigenic potential, as evidenced by decreased tumor size, repressed tumor growth and reduced tumor weight." (PMID 32513235, 2020). "The influence of SALL4 expression on ccRCC tumor growth, metastasis and vascularity was evaluated through a series of in vitro and in vivo experiments." (PMID 32513235, 2020). "Despite the protumorigenic and prometastatic activities of SALL4 in tumor progression, our results unveiled a novel role for SALL4 in angiogenesis." (PMID 32513235, 2020). "In this report, we discovered that SALL4 is frequently overexpressed in ccRCC patients and positively correlated with tumor progression." (PMID 32513235, 2020). "The previous studies have shown that SALL4 is involved in tumor cell proliferation, migration, invasion, DNA damage repair, and drug resistance, suggesting a high potential of SALL4 as tumor biomarker and therapeutic target." (PMID 32489324, 2020). "Overall, our results provide evidence that upregulated SALL4 can function as a crucial regulator of tumor pathogenesis and progression in ccRCC, thus offering potential therapeutic strategies for future treatment." (PMID 32513235, 2020). "Our results revealed that SALL4 expression positively correlated with T stage, tumor grade and AJCC stage (P < 0.05)." (PMID 32513235, 2020). "We found that dMyc is repressed in sal/SALL4-expressing regions and introducing dMyc partially rescues cell invasion, indicating a repressive role of dMyc in tumor cell migration." (PMID 32098783, 2020). "Increasing evidence suggest that SALL4 promotes tumor growth, metastasis, and therapy resistance through the regulation of c-Myc, TGF-β1, ATP-binding cassette (ABC), among others." (PMID 32489324, 2020). "Further investigations have indicated that SALL4 can drive tumor metastasis via induction of epithelial-mesenchymal transition (EMT) or direct transcriptional upregulation of c-Myc." (PMID 32513235, 2020). "The tumor suppressor PTEN has been reported to be a target gene repressed by SALL4 and counteract the PI3K pathway." (PMID 32513235, 2020). "The epithelial-mesenchymal transition has been reported to be involved in SALL4-mediated tumor metastasis." (PMID 32513235, 2020). "SALL4 expression was increased in ccRCC and positively correlated with tumor progression and poor prognosis." (PMID 32513235, 2020). "Among the six hypomethylated SALL4 regions, a negative correlation between methylation status of chr20:51800437 and chr20:51800155 and SALL4 mRNA expression was observed in both ccRCC tumor samples and paired normal kidney samples." (PMID 32513235, 2020). "Our data indicated that SALL4 downregulation attenuated ccRCC tumor growth, metastasis and angiogenesis." (PMID 32513235, 2020). "In summary, we provide evidence that upregulated SALL4 expression is strongly correlated with tumor progression and poor prognosis in ccRCC." (PMID 32513235, 2020). "SALL4 is overexpressed in cancer cells and affects multiple cellular processes that are involved in tumorigenesis, tumor growth, and tumor progression." (PMID 31650028, 2019).
tumor (continued). "BRM270 significantly represses the proliferation and metastasis and deactivates SALL4-mediated CSCs maintenance and Shh expression and activities, thus favoring antipancreatic tumor treatment." (PMID 31049070, 2019). "(D) and (E) Gene expression levels of SALL4 in different cancer cell lines (in D) and in tumor tissues (in E) using Real-time PCR analyses." (PMID 29625565, 2018). "Further, SALL4 activation participates in the pathogenesis of tumor initiation and disease progression." (PMID 29308206, 2018). "Regarding the role of self-renewal factors such as SOX2, NANOG, KLF4, and SALL4 in biology of tumor cells we assessed the probable role of KCTD12 in regulation of such factors in the levels of mRNA expression." (PMID 30157793, 2018). "Other groups have also indicated that miRNA-98, miRNA-33b, and miRNA-219 play tumor-suppressive roles in cancer by targeting SALL4." (PMID 30423818, 2018). "DANCR is upregulated by SALL4 and exerts its tumor-promoting roles partly through the activation of β-catenin pathway." (PMID 29416741, 2018). "We then performed Cox multivariate regression analysis by adding tumor metastasis, TNM stages, tumor volume, SALL4, miR-200c, and PD-L1 into a model." (PMID 29593314, 2018). "Here, we report that the expression of Sal-like protein 4 (SALL4), was significantly higher in EGFR mutated lung tumors than in non-tumor tissue." (PMID 29691367, 2018). "We analyzed the relationship among SALL4, miR-200c, and PD-L1 expression in the center tumor regions from each HCC patient." (PMID 29593314, 2018). "The recent studies suggest that SALL4 plays active roles in tumor growth, metastasis and therapy resistance." (PMID 29416741, 2018). "In recent years, there have been gains in our understanding of SALL4-regulated molecular mechanisms and SALL4-targeted strategy in killing tumor cells." (PMID 29308206, 2018). "Abnormally high expression of SALL4 was closely related to tumor formation and prognosis in hematopoiesis and leukemogenesis, but SALL4 was also required for DNA damage response in ESCs, ensuring their stability during expansion." (PMID 28887597, 2017). "For example, in NB4 AML cells transduced with lentiviral-SALL4, there was an overall increased percentage of DNA methylation at various CpG sites of the tumor suppression gene PTEN promoter and SALL4 promoter itself." (PMID 28974232, 2017). "Both SOX2 (brown) and SALL4 (brown) showed positive nuclear staining with increased expression especially toward the periphery of the tumor nests." (PMID 27532037, 2016). "The overexpression of SALL4 in tumor patients often correlates with adverse progression and poor prognosis." (PMID 26935744, 2016). "SOX2 (red) and SALL4 (green) were co-expressed (appearing as orange) by cells within the tumor nests and the stroma, and the endothelium of the microvessels (red)." (PMID 27532037, 2016). "The detection of a EMA+/CD44+/SOX2+/OCT4+/SALL4+/pSTAT3+/NANOG+ subpopulation within the tumor nests aligns with recent literature reporting localization of CSC in OCSCC, particularly at the “tumor front”." (PMID 27532037, 2016). "SALL4 was an indicator of stem cells and a prognostic marker in hepatocarcinogenesis, relative to cell and tumor growth, with chemoresistance to 5-FU, and its suppression resulted in differentiation and slowed tumor growth." (PMID 27610139, 2016). "ATIIR2 (red) was expressed by cells within the tumor nests that have been shown to express SALL4 (green)." (PMID 27730124, 2016). "Taken together, these results indicate that CD44 overexpression antagonizes SALL4 knockdown-mediated inhibition of tumour growth in vivo." (PMID 27819668, 2016). "Taken together, these results suggest that knockdown of SALL4 reduces tumor burden and inhibits tumor formation in vivo." (PMID 27329034, 2016). "The role of SALL4 was‏ the focus on carcinogenesis, prevention, treatment of‏ tumor cell lines, and tumor tissues." (PMID 28959334, 2016).